SIX1 (SIX homeobox 1)
Diseases named in the same sentence as SIX1 in open-access papers (continued):
Sharing a sentence is not in itself a finding about the gene and the disease.
melanoma (continued). "However, the role of SIX1 and the upstream regulators of SIX1 in melanoma are largely unknown." (PMID 32258386, 2020). "Interestingly, melanoma patients with increased glucose uptake and metastasis assessed by 2-18fluoro-2-deoxy-d-glucose positron emission tomography (18FDG PET) scans displayed decreased miR-489-3p expression and increased expression of SIX1." (PMID 32258386, 2020).
asthma (9 papers, 2020 to 2025). "Down-regulation of NEAT1 reduced the Six1 expression via targeting miR-204-5p to inhibit the process of EMT in asthma." (PMID 39423195, 2024). "SIX1 level was up-regulated in asthma serum samples and induced by TGF-β1 treatment in human bronchial epithelial cells." (PMID 32065213, 2020). "Compared with the control group, the level of miR-203a-3p was significantly decreased in asthma serum samples (P = 0.0021), while SIX1 expression was markedly increased in asthma serum samples (P < 0.0001)." (PMID 32065213, 2020). "In the present study, we investigated the expression and the roles of miR-203a-3p and SIX1 in asthma, and elucidated the regulatory relationship among miR-203a-3p, SIX1 and Smad3 in the development of asthma." (PMID 32065213, 2020). "The miR-106B-5p/E2F1/SIX1 signaling pathway may represent a potential therapeutic target for asthma." (PMID 39911398, 2025). "In asthma mice, the reduction of Six1 expression inhibited TGF-β1-induced EMT." (PMID 39423195, 2024). "In addition, miR-204-5p inhibited the proliferation and extracellular matrix (ECM) production of airway smooth muscle cells (ASMC) by regulating Six1 in asthma." (PMID 39423195, 2024). "The miR-128-3p/SIX1 axis was thus recognised to be an important mechanism in the pathophysiology of asthma, and the authors posited that it could offer a new therapeutic target." (PMID 39125612, 2024). "The results suggested that the miR-448-5p/TGF-β1/SIX1 axis may be a novel target for strategies to prevent airway remodeling in asthma." (PMID 36750914, 2023). "Moreover, mutations of SIX1 or EYA contribute to branchio-oto-renal (BOR) syndrome, muscle defects, asthma, etc.." (PMID 36750914, 2023). "A complex pathway that could be a future therapeutic target for asthma is the miRNA-106b-5p/E2F1/SIX1." (PMID 37511254, 2023). "Interestingly, we also found that SIX1 level was opposite correlated with miR-203a-3p expression in asthma serum samples." (PMID 32065213, 2020). "MiR-203a-3p was down-regulated and SIX1 was up-regulated in asthma serums, respectively." (PMID 32065213, 2020). "Thus, the miR-448-5p/SIX1 signaling may play a critical role in the process of EMT and subepithelial fibrosis associated with asthma." (PMID 39911398, 2025). "Other studies presented the role of miR-204-5p in interfering with TGFβ signaling pathways through regulating Six1 and SMAD4 genes in airway smooth muscle cells of asthma and human posterior capsule opacification, respectively." (PMID 38632250, 2024). "Based on the axis of miR-203a-3p/SIX1 in BEAS-2B and 16HBE cells, we further investigated whether SIX1 involved in miR-203a-3p mediated regulation on the EMT in asthma." (PMID 32065213, 2020). "Our findings demonstrated that miR-203a-3p was down-regulated in asthma serums, and overexpressed miR-203a-3p inhibited TGF-β1-induced EMT in asthma by regulating Smad3 pathway through targeting SIX1, suggesting a promising therapeutic approach for bronchial epithelial cell EMT in asthma." (PMID 32065213, 2020). "Additionally, recent study has indicated that SIX1 was remarkably elevated in asthmatic mice and played a major role in transforming growth factor-β (TGF-β1)-induced EMT and pulmonary fibrosis in asthma." (PMID 32065213, 2020). "Notably, a negative correlation between miR-203a-3p and SIX1 in asthma serum samples was observed (P < 0.001, R2 = 0.2591)." (PMID 32065213, 2020).
cervical cancer (9 papers, 2014 to 2025). A primary or metastatic malignant neoplasm involving the cervix. "More recently, we linked the switch in TGFβ signaling pathways in HPV16-transformed cells to alterations of the expression of the homeobox transcription factor SIX1, linked to invasiveness and aggressive behavior in a variety of cancers, including cervical cancer." (PMID 25632320, 2014). "SIX1 promotes EMT in cervical cancer cells via the TGF-β/SMAD signaling pathway, in contrast to DACH1." (PMID 36750914, 2023). "With regard to miR-889-3p function, lncRNA XIST modulates the miR-889-3p/SIX1 axis and participates in cervical cancer progression." (PMID 34858987, 2021). "Many studies have indicated that SIX1, an important oncogene, was found to be overexpressed in various cancers including pancreatic, breast ovarian and cervical cancers." (PMID 28573504, 2017). "Notably, E7 oncogene stimulates SIX1 expression in cervical intra-epithelial neoplasia and cervical cancer cells and accumulation of cyclin D1 in tumor cells, resulting in tumorigenesis." (PMID 39863145, 2025). "Similarly, the up-regulation of SIX1 expression in cervical cancer induces EMT to enhance the proliferation, invasion, and migration of cells." (PMID 36750914, 2023). "While overexpression of SIX1 is clearly detected in a subset of cervical cancers (; unpublished observations) and is linked to advanced disease when detected in any solid tumors, a role for SIX1 in HPV-driven HNC has not yet been proposed." (PMID 25632320, 2014).
endometrial cancer (9 papers, 2020 to 2025). Primary or metastatic malignant neoplasm involving the endometrium (mucous membrane that lines the endometrial cavity). "When neonatal mice were exposed to DES, SIX1 is increased dramatically over time in the uteri at 6, 12, and 18 months of age and was associated with the development of endometrial cancer." (PMID 40362361, 2025). "Previous studies demonstrated that Six1 promoted cell proliferation, migration and invasion in endometrial cancer." (PMID 32220051, 2020). "In endometrial carcinoma, SIX1 overexpression promotes cell growth through extracellular signal-regulated kinase (ERK)- and AKT-mediated pathways." (PMID 32258386, 2020). "Particularly, a recent study demonstrated that Six1 is overexpressed in endometrial carcinoma and promotes the malignant behaviour of cancer cells via ERK and AKT signalling." (PMID 32220051, 2020). "Consistently, the high expression of SIX1 in endometrial cancer could be a predictor of unfavourable prognosis in these patients." (PMID 35201514, 2021). "MiR-23a inhibited endometrial cancer by targeting sine oculis homeobox homolog 1 (SIX1)." (PMID 33413440, 2021). "Furthermore, the elevated expression of SIX1 is a biomarker of hyper- or dysplastic cells in human endometrial cancers." (PMID 32120995, 2020). "SIX1 was not present in normal endometrium but was expressed in a subset of endometrial cancers in patients who were also more likely to have late-stage diseases." (PMID 35205261, 2022).
liver cancer (9 papers, 2015 to 2024). An epithelial or non-epithelial malignant neoplasm that arises from the liver. "In patients with liver cancer, SIX1 expression is positively correlated with DGUOK‐AS1 and SCD1 expression and is negatively correlated with microRNA‐145‐5p expression." (PMID 39258807, 2024). "Contrary to SIX1 overexpression, SIX1 KO (knockout) in HepG2 liver cancer cells and SIX1 KD in MHCC97H and SMMC‐7721 liver cancer cells reduced mRNA expression of ACLY, ACC1, FASN, and SCD1, and protein expression of ACLY, FASN, and SCD1." (PMID 39258807, 2024). "This study demonstrates that transcription factor SIX1 regulates de novo lipogenesis (DNL) in liver cancer by recruiting histone acetyltransferases AIB1 and HBO1 to DNL‐related gene promoters." (PMID 39258807, 2024). "The DGUOK‐AS1/microRNA‐145‐5p/SIX1 axis regulates liver cancer cell proliferation, invasion, and metastasis in vitro and in vivo." (PMID 39258807, 2024). "In this study, we found that DGUOK‐AS1 contributes to liver cancer cell growth and metastasis through miR‐145‐5p mediated modulation of SIX1 expression and SIX1‐regulated lipogenesis." (PMID 39258807, 2024). "Compared to normal liver tissues, SIX1 phosphorylation at S225 (pS225) is upregulated in human liver cancer tissues." (PMID 39617783, 2024). "Given the importance of the upregulation of SIX1 in numerous types of cancer, especially liver cancer, the role of the SIX1 transcription factor in HCC was subsequently investigated." (PMID 37427884, 2023). "In liver cancer, SIX1 expression was a prognostic factor for survival that is independent of CD90 expression." (PMID 37427884, 2023). "The upregulation of SIX1 expression levels in liver cancer samples prompted the study into its expression levels with immunohistochemistry (IHC)." (PMID 37427884, 2023). "Following these cDNA array results, the bioinformatics analysis also produced a similar SIX1 expression profile, with the highest expression levels detected in liver cancer." (PMID 37427884, 2023). "The goal of this study was to determine the expression profile of SIX1 in various types of cancer, in which the highest expression levels were detected in liver cancer." (PMID 37427884, 2023). "We have found that SIX1 promotes aerobic glycolysis and is upregulated in various human cancers, such as breast infiltrative ductal carcinoma, liver cancer, and lung cancer." (PMID 32258386, 2020). "Recently, evidence has shown that SIX1 is overexpressed in various cancers including breast, ovarian, colorectal and liver cancer 10-12, 15-17." (PMID 32201523, 2020). "The findings of this study revealed that SIX1 might be used as a biomarker for liver cancer progression." (PMID 37427884, 2023). "Taken together, these data suggested that the upregulation of the SIX1 mRNA and protein expression levels may be an important indicator of the progression of liver cancer." (PMID 37427884, 2023). "Our analysis predicted several potential SIX1-targeting miRNAs, among which only miR-489-3p and the positive control miR-548a-3p, which has been shown to inhibit SIX1 expression in breast and liver cancer cells, could inhibit SIX1 expression in 293T cells by western blot analysis." (PMID 32258386, 2020). "Consistent with the results using liver cancer cell lines, SIX1 bound to the DNL‐related gene promoters and altered the promoter epigenotypes by recruiting AIB1 and HBO1 in liver cancer tissues." (PMID 39258807, 2024). "In a parallel mechanism, TUG1, derived from CAFs, enters liver cancer cells and engages in the TUG1/miR-524-5p/SIX1 pathway, facilitating SIX1-driven glycolysis through the “ceRNA” mechanism." (PMID 39717771, 2024). "Since the DGUOK‐AS1/miR‐145‐5p/SIX1 axis is dysregulated in cancer, correlates with prognosis, and controls DNL, and SIX1 KO attenuates NAFLD progression, this axis is expected to be a promising therapeutic target for curing liver cancer and NAFLD." (PMID 39258807, 2024).
liver cancer (continued). "DGUOK‐AS1/microRNA‐145‐5p/SIX1 axis strongly links DNL to tumor growth and metastasis and may become an avenue for liver cancer therapy." (PMID 39258807, 2024). "Thus, the DGUOK‐AS1/microRNA‐145‐5p/SIX1 axis strongly links DNL to tumor growth and metastasis and may become an avenue for liver cancer therapeutic intervention." (PMID 39258807, 2024). "In liver cancer cells, the insulin/DGUOK‐AS1/miR‐145‐5p axis did not alter the histone acetylation at the SIX1 promoter, suggesting that the insulin/DGUOK‐AS1/miR‐145‐5p axis may not regulate SIX1 expression at the transcriptional level." (PMID 39258807, 2024).
rhabdomyosarcoma (9 papers, 2010 to 2023). A rare aggressive malignant mesenchymal neoplasm arising from skeletal muscle. "SIX1 promoted cyclin D1 transcription in rhabdomyosarcoma cells, leading to tumor initiation, and SIX1 also facilitated BC cell proliferation via inducing cyclin A expression." (PMID 36750914, 2023). "Ezrin, a cytoskeleton regulator protein, is a SIX1 direct transcriptional target in rhabdomyosarcoma." (PMID 34771571, 2021).
ovarian carcinoma (7 papers, 2013 to 2024). A malignant neoplasm originating from the surface ovarian epithelium. "Previous studies reported that the upregulation of SIX1 expression levels was associated with a poor prognosis in breast, lung, pancreatic, cervical, colorectal, and ovarian cancers." (PMID 37427884, 2023). "In ovarian carcinoma, overexpression of SIX1 causes resistance to tumor necrosis factor-related apoptosis-inducing ligand (TRAIL)-mediated apoptosis." (PMID 32258386, 2020). "The SIX1 expression and drug resistance studies showed that SIX1 and drug responses are inversely related; SIX1 downregulation caused drug sensitivity, and SIX1 overexpression enhanced drug resistance in breast and ovarian cancer cells." (PMID 37427884, 2023). "Taken together, our data demonstrated miR-488 inhibits chemoresistance in ovarian cancer through downregulation of Six1." (PMID 29113360, 2017). "We also demonstrated that Six1 could maintain mitochondrial membrane potential in ovarian cancer cells." (PMID 29113360, 2017). "Six1 is an oncoprotein which was overexpressed in ovarian cancer." (PMID 29113360, 2017). "Moreover, Six1 overexpression in ovarian cancer promotes the proliferative phenotype of the tumor cells." (PMID 23527134, 2013). "Indeed, endogenous Six1 regulates SHH expression in A2780 ovarian cancer cells." (PMID 28604738, 2017).
deafness (6 papers, 2017 to 2025). An inherited or acquired condition characterized by the complete loss of the ability to hear from one or both ears. "These cells expressed several causal genes for various deafness forms, including Eps8l2, Gjb2, Gjb6, Homer2, Coch, Clic5, Dcdc2a, Pou3f4, Col4a6, and Six1." (PMID 37339214, 2023). "Finally, we show that most putative chick Six1 targets are also expressed in the human developing ear and are associated with known deafness loci." (PMID 40213817, 2025). "Together, our findings implicate these newly identified putative Six1 targets as new candidate deafness genes." (PMID 40213817, 2025). "To determine whether the newly identified candidate Six1 target genes represent candidate deafness genes in humans, we first performed RNA-sequencing (RNAseq) from dissected otic vesicles and from the adjacent dorsal hindbrain from CS13 and CS14 human embryos." (PMID 40213817, 2025). "They found that numerous deafness-related genes (e.g. Col9a2, Lmx1a, and Sox10) were downregulated, and single-cell transcriptome data from Chd7KO/+ organoids also showed that some deafness-related genes (e.g. Six1, Ush1c, and Strc) were downregulated in HCs, implying that." (PMID 38015350, 2024). "Interestingly, the genomic location of many putative Six1 targets coincides with human deafness loci where the causative gene remains to be identified, introducing previously unreported candidate deafness genes for BOR or other forms of deafness." (PMID 40213817, 2025). "Finally, we assessed whether the human putative Six1 targets represent new candidate deafness genes." (PMID 40213817, 2025). "In summary, the identification of new candidate Six1 target genes not only provides new information on the mechanisms of inner ear progenitor information during development, but has also allowed us to propose new candidate genes for BOR/BOS and other forms of deafness." (PMID 40213817, 2025).
glioma (6 papers, 2019 to 2023). A benign or malignant brain and spinal cord tumor that arises from glial cells (astrocytes, oligodendrocytes, ependymal cells). "Primarily, miR-155-3p acts as an oncogene via the direct inhibition of tumour suppressors such as TP53INP1 (adenocarcinoma), FBXW7 (hepatocellular carcinoma), PCDH7/CREB3/SIX1 (glioma), WDR82 (colorectal cancer) and CADM1 (breast cancer)." (PMID 35611569, 2022). "The role of Six1 on miR‐155‐3p‐mediated TMZ resistance in glioma cells was assessed by cotransfecting human Six1 plasmids and mimics of miR‐155‐3p into A172 and U87 cells." (PMID 32220051, 2020). "After transfecting A172 and U87 cells with miR‐155‐3p, the role of Six1 was evaluated on the growth‐promoting role of miR‐155‐3p in glioma cells by cotransfecting miR‐155‐3p mimics and human Six1 plasmids into A172 and U87cells." (PMID 32220051, 2020). "Thus, miR‐155‐3p modulates Six1 expression and facilitates the progression of glioblastoma and resistance to temozolomide and may act as a novel diagnostic biomarker and a target for glioma treatment." (PMID 32220051, 2020). "Further, we found that Six1 is targeted directly by miR‐155‐3p and in an inverse relationship in glioma." (PMID 32220051, 2020). "Bioinformatics analyses, and assays using luciferase reporter, and immunoblotting revealed that miR‐155‐3p targets Six1 and that the relationship between glioma and healthy brain tissues was significantly inverse." (PMID 32220051, 2020). "Further studies with human glioma cells have confirmed these observations and clearly support the link of the pro-tumorigenic effect of SIX1 with senescence escape and SOX2-mediated self-renewal." (PMID 30723235, 2019). "Moreover, miR-155-3p has also been demonstrated to directly inhibit homeobox protein SIX1 in glioma, with reintroduction of SIX1 found to rescue the TMZ resistance induced by miR-155-3p mimic administration." (PMID 35611569, 2022). "Particularly, we found an amplified enhancer-SIX1-MYC regulation in glioma." (PMID 33537074, 2021). "Thus, Six1 overexpression reverses resistance to TMZ in glioma cells with high levels of miR‐155‐3p." (PMID 32220051, 2020). "We demonstrated in this study that Six1 could be developed as a therapeutic target for glioma patients because of its vital roles in glioma." (PMID 32220051, 2020). "Nevertheless, Six1 is not the only mode of affecting TMZ resistance in glioma, and some potential ways independent of Six1 mutation have possibly not been discovered." (PMID 32220051, 2020). "Our findings also showed low level of Six1 in glioma cells than NHAs." (PMID 32220051, 2020). "Moreover, functional analyses with human glioma cell lines also show that SIX1 controls SOX2 expression, senescence and self-renewal in this model." (PMID 30723235, 2019). "Thus, the function of Six1 is targeted by miR‐155‐3p in glioma cells." (PMID 32220051, 2020). "GO terms related to TGF-β receptor activity are significantly enriched among the SIX1 downstream targets, which links TGF-β signalling via SMAD3 to the synaptic communication between neurons and glioma cells." (PMID 37833281, 2023). "In addition, Six1 levels were measured in 20 high‐grade and 20 low‐grade tissues of glioma and 20 non‐cancerous tissues of the brain, and significant decline in Six1 proteins levels in low‐grade or high‐grade glioma specimens was observed compared with that in normal brain tissue." (PMID 32220051, 2020). "To this end, we focused in glioma, because SIX1 and SOX2 are frequently overexpressed in these tumors and they are both specifically enriched in glioma stem cells." (PMID 30723235, 2019). "In line with our observations, inspection of datasets from the TCGA collection reveals a significant correlation between SIX1 and SOX2 expression in different tumor types, including glioma, soft-tissue sarcoma, prostate and esophageal cancer." (PMID 30723235, 2019).
glioma (continued). "To study the link between SIX1 and SOX2 in glioma, we used the cell lines U251 and GNS16626, representative of differentiated and stem-like phenotypes respectively." (PMID 30723235, 2019). "Both SIX1 and MYC were upregulated in patients with glioma with amplified enhancer." (PMID 33537074, 2021). "Notably, silencing of SIX1, using two independent shRNAs, led to a marked reduction in SOX2 transcript and protein in both glioma cell lines, in line with the results in mouse transformed fibroblasts." (PMID 30723235, 2019).